IRS2 (insulin receptor substrate 2)
Diseases named in the same sentence as IRS2 in open-access papers (continued):
Sharing a sentence is not in itself a finding about the gene and the disease.
tumor (continued). "A role for IRS2 in tumor cell invasion was established in our previous studies using cells chronically lacking IRS2 expression through Cre-lox recombination or CRISPR/Cas9-mediated gene knockout." (PMID 39305958, 2024). "In particular, the expression of WNT inhibitory factor 1 (Wif1), a canonical tumor suppressor, and insulin receptor substrate 2 (Irs2), were decreased with age in both Glut4m and WT mice." (PMID 38161415, 2024). "Irs2 contributes to both the initiation of primary tumor growth and the establishment of secondary metastases through regulation of CSC function and invasion in response to IIS." (PMID 39305958, 2024). "Many studies have found that IRS-1 negatively regulates tumor progression, whereas IRS-2 promotes tumor behavior through metabolism regulation." (PMID 36831374, 2023). "In particular, IRS2 has been shown to affect tumor progression and metastasis, largely through its ability to respond to the metabolic microenvironment." (PMID 35816477, 2022). "IRS2, a direct PR target gene, controls various downstream signaling cascades primarily affecting glucose metabolism for growth and survival of tumor cells." (PMID 35816477, 2022). "The IRS-2 located on chromosome 13q34 is primarily a progesterone response gene, mediates glucose metabolism and tumor progression." (PMID 34784930, 2021). "IRS2 is expressed in various types of cancer and has been reported to contribute to tumour cell metabolism." (PMID 33570213, 2021). "Tumorigenesis after EC9706 inoculation in mice revealed that silencing YAP inhibited the progression of EC and reduced tumour size and weight, which was neutralized following the overexpression of IRS2." (PMID 33570213, 2021). "Here, we provide several lines of evidence to suggest that PP1, IRS‐1/2, and pRb (p105) are involved in the TGF‐β‐stimulated TβR‐V‐mediated tumor suppressor signaling cascade (TβR‐V/IRS‐2/PP1/pRb)." (PMID 34485840, 2021). "Tumor samples showed a statistically significant downregulation of miR-7-5p and upregulation of IRS2 and EGFR, compared to their matched normal tissues." (PMID 34381564, 2021). "Although IRS-1 and IRS-2 share significant homology, they regulate distinct functional outcomes in tumor cells." (PMID 31393907, 2019). "While a tendency towards increased tumor Irs2 mRNA expression was also noted, the increase in the tumor: non-tumor tissue expression ratio was significantly higher for Irs1 mRNA than for Irs2 mRNA." (PMID 28710407, 2017). "As IRS2 is the more definitive mediator of tumor progression and metastasis, we focused our studies on IRS2." (PMID 27765041, 2016). "On the other hand, 99% (82/83) of the PTC patients exhibited L-Selectin expression and the IRS-9 was observed as the median score and VCAM-1 expression was positive in 84% (70/83) of the tumours with median score as IRS-2." (PMID 26881177, 2016). "Additional support for IRS-2 as a positive regulator of tumor progression comes from in vivo mouse model studies." (PMID 19534786, 2009). "One possible mechanism by which IRS-2 contributes to tumor progression and cell invasion is by positively regulating aerobic glycolysis via the enhanced localization of the GLUT-1 glucose transporter on the tumor cell surface." (PMID 19534786, 2009). "The two Irs2 insertions must therefore have occurred first and in the same tumor cell followed by the two Il2rg insertions in different subpopulations of tumor cells." (PMID 19461887, 2009). "The Irs2 insertion was present at about one copy per cell, indicating it is present in every tumor cell." (PMID 19461887, 2009). "The other Irs2 insertion must therefore be in the same tumor cell, either on the same or different chromosome." (PMID 19461887, 2009).
tumor (continued). "Both of these signaling pathways have been implicated in promoting tumor cell proliferation, invasion and survival, but they cannot explain the differential abilities of IRS-1 and IRS-2 to regulate these functions." (PMID 19534786, 2009). "Consistent with the in vitro experiments, HCT116IRS2 cells formed larger tumors and exhibited accelerated growth (by 304% 21 days after injection, P = 0.03), whereas, LS513sh-IRS2 cells showed decreased tumor outgrowth (by 247% 25 days after injection, P = 0.005)." (PMID 39888380, 2025). "IRS2 plays a role in tumor development through the PI3K/AKT pathway." (PMID 41050263, 2025). "IRS2-expressing cells retained their growth advantage when exposed to microglia CM but not to lung CM or in the in vivo subcutaneous tumor model." (PMID 39888380, 2025). "The contributions of IRS2 to tumor cell biology have been revealed through studies using cell and mouse model systems in which the IRS2 gene has been genetically knocked out by Cre-lox recombination or CRISPR/Cas9-mediated gene editing or knocked down by shRNA." (PMID 39305958, 2024). "Moreover, the acute induction of IRS2 degradation reduces tumor cell invasion, demonstrating the potential for therapeutic targeting of this adaptor protein." (PMID 39305958, 2024). "The Insulin Receptor Substrate (IRS) adaptor proteins IRS1 and IRS2 play essential roles in regulating the response of breast and other tumor cells to signaling through the insulin (IR) and Insulin-like Growth Factor-1 (IGF-1R) receptors, as well as to some integrin and cytokine receptors." (PMID 39305958, 2024). "To additionally validate these results, we also evaluated the native IRS2 protein and its phosphoprotein in a panel of tumor cell lines by using an antibody specific for the phosphorylated IRS2 protein (against pSer1100), as well as an antibody that recognizes total IRS2 protein." (PMID 35260532, 2022). "Similarly, IRS2 was identified as a downstream target of miR-195-5p, and overexpressing miR-195-4p inhibited tumor development by decreasing IRS2 expression." (PMID 36142352, 2022). "Tumor samples showed a downregulation of miR-7-5p and conversely an upregulation of IRS2 and EGFR." (PMID 34381564, 2021). "In the univariate analysis, surgery palliative care, histopathological phenotype (gastric and pancreatic type), presence of lymph node metastases, higher TNM stage, tumor metastasis, and high expression of ATG12 and IRS2 were all associated with poor prognosis." (PMID 34976838, 2021). "Irs2 plays requisite roles in cell proliferation, apoptosis, migration, and tumor invasion." (PMID 35127549, 2021). "Alternatively, IRS-1 and IRS-2 may independently regulate their functional outcomes through the formation of unique scaffolding interactions, with the ability of IRS-2 to promote tumor progression being dominant to the suppressive activity of IRS-1." (PMID 31393907, 2019). "Since STAT5 activation decreases apoptosis and induces malignant transformation and tumor progression, the STAT5 downregulation promoted by IRS2 inhibition may contribute to the reduced tumor proliferation and survival in HEL cells." (PMID 26755644, 2016). "Also, the inverse relationship between expression of let-7b and IGF-1R/IRS-2 was confirmed in OSCC tumor xenografts and clinical specimens." (PMID 24810113, 2014). "One potential mechanism for IRS-specific regulation of tumor cell functions is the recruitment of effectors to unique binding motifs in the C-termini of the IRS proteins that activate signaling pathways selectively downstream of either IRS-1 or IRS-2." (PMID 19534786, 2009).
tumor (continued). "Moreover transgenic overexpression of IRS-1 or IRS-2 in the mammary gland results in hyperplasia, tumor development and metastasis." (PMID 19534786, 2009). "Likewise, tumor 7107 has two insertions at Irs2, another highly significant result (p = 1.16×10−5, see Text S1 for calculation)." (PMID 19461887, 2009). "Importantly, suppression of Irs-2 expression in Irs1-/- tumor cells restores mTor activation to wildtype levels, confirming the contribution of Irs-2 to the increased mTor activity." (PMID 19534786, 2009). "IRS-2 might contribute to tumor malignancy by promoting the secretion of factors." (PMID 37894751, 2023). "Therefore, IRS-2 may promote tumor progression by stimulating a positive feedback loop to enhance IGF-1 signaling." (PMID 19534786, 2009). "In this study, we evaluated the expression levels of HIC1, AR, IRS2, and EMT‐related proteins, as well as the activation status of the PI3K/AKT pathway in PCa mouse tumor tissue using RT‐qPCR and Western blot experiments." (PMID 41050263, 2025). "We also identified C-CBL as an E3 ligase responsible for neddylating IRS1 and IRS2, with clinical evidence further confirming a reciprocal relationship between C-CBL and pAKT, thereby reinforcing the tumor suppressive role of C-CBL." (PMID 38272982, 2024). "IRS2 and PPP1R3C, are involved in glycogen synthesis, and are among the downregulated genes in monosomy 3 tumours; both had a lower expression in UMs with epithelioid cells in a study performed on UMs using data from the TCGA." (PMID 37240204, 2023). "We detected significant downregulation of IRS2 and NT5E in tumor tissues, whereas CACNA1H, CHPF, SDC1 and ATP6AP1 were highly expressed in tumor tissues than in normal tissues." (PMID 36277284, 2022). "The results showed that the transcriptional expression levels of NDRG1 (P < 0.001), ERRFI1 (P < 0.001), IRS2 (P < 0.001), IGFBP4 (P < 0.01), and BIRC3 (P < 0.01) were significantly decreased in tumor tissues, while SOCS1 (P < 0.05) expression was increased." (PMID 35859293, 2022). "The NT compounds are highly effective in anti-cancer activity because they inhibit both the tumor growth promoted by IRS-1 and IRS-2-mediated metastasis." (PMID 36551732, 2022). "At molecular level, circFAT1 sequestered miR-7 to upregulate IRS2, which in turn regulated downstream ERK1/2 phosphorylation and CCND1 expression, ultimately promoting tumor progression." (PMID 35844799, 2022). "Tumour formation in the nude mice was detected in order to ascertain the effect of YAP and IRS2 in vivo." (PMID 33570213, 2021). "Under parous (p) and nulliparous (np) conditions, median time to tumor formation (MTTF) was similar for both ErbB2 (p = 214 and np = 244 days) and ErbB2/IRS2 bigenic mice (p = 211 and np = 264 days)." (PMID 27765041, 2016). "Here, we demonstrated that this compound inhibits tumor growth, cell cycle, and the motility of OS cells via the downregulation of IRS-1/IRS-2 proteins and their downstream mediators." (PMID 26029165, 2015). "In order to validate these data and corroborate the association between the genomic data and protein expression, we examined the IRS2 expression using IHC staining of human CRC samples from BM (n = 56), liver metastasis (LM) (n = 49), and primary tumor (n = 12)." (PMID 39888380, 2025). "IRS2 contributes to more aggressive tumor behavior through its ability to regulate CSC self-renewal to promote tumor initiation at both primary and metastatic sites and through the regulation of tumor cell invasion." (PMID 39305958, 2024). "Furthermore, extensive correlations between IRS-1 and IRS-2, RUNX3 and SMAD4 in tumor and stroma, were observed (0.15 < r < 0.60)." (PMID 36900240, 2023).
tumor (continued). "The patient’s tumor also carried VUSs in the AKT/mTOR pathway genes AKT1 and IRS2." (PMID 37202426, 2023). "Upon sequencing a biopsy obtained from the post-progression tumor, we identified the acquisition of a focal amplification of IRS2 that was absent from the AKT inhibitor-naïve tumor at trial enrollment." (PMID 35440569, 2022). "In addition, we also found that Ki67, IRS2 and CCND1 protein were upregulated in tumor tissues by an immune-fluorescence assay, which is consistent with the observations in vitro." (PMID 35844799, 2022). "Finally, for IRS2, RRS2 and MRPL5, we found comparable effects on gene expression under tumour conditions or exposure to BPA." (PMID 34062972, 2021). "When IRS-2/PI3K/p70S6K pathway is constitutively activated, the direct binding of IRS-2 with IGF-IR, regardless of IGF-I stimulation, induces downstream effects that lead to tumor cell proliferation and inhibition of apoptosis." (PMID 27661006, 2017). "In the attempt to confirm whether the effects of IGF-1R and IRS-2-mediated let-7b on proliferation observed in OSCC cells and clinical specimens were related to tumor growth." (PMID 24810113, 2014). "Notably, IRS-1 and IRS-2 are upregulated in HCC and actively support the tumour phenotype." (PMID 38710924, 2024). "Particularly, in GB, miR-7 was shown to act as a tumor suppressor miRNA, as it directly targets the epidermal growth factor receptor (EGFR) gene and negatively regulates the AKT signaling pathway through the direct inhibition of its upstream regulator, the insulin receptor substrate 2 (IRS2)." (PMID 38473710, 2024). "Overexpression of IRS2 may result in AKT phosphorylation, thus promoting tumor progression." (PMID 26684807, 2015). "Knockdown of MAML2 significantly affected cell colony formation in vitro, the knockdown of EMP1, IRS2, and SP100 did not affect tumor growth or metastasis." (PMID 40781158, 2025). "Irs-2 expression is elevated in tumors that arise in PTEN+/- mice, and deletion of Irs-2 has no impact on tumor initiation, but it does suppress tumor growth and progression to invasive disease." (PMID 19534786, 2009). "The distinct functions of IRS-1 and IRS-2 in tumor progression may reflect a differential sensitivity of IRS-1 and IRS-2 to the effects of negative feedback regulation, which could alter the longevity and intensity of signals initiated through each adaptor protein." (PMID 19534786, 2009).
metabolic disorders (6 papers, 2012 to 2025). "The lower expression of the IRS2 gene in the patients with a higher body-mass index also suggested the presence of a systemic metabolic disorder in a subgroup of the UM patients." (PMID 32751097, 2020).
infection (5 papers, 2009 to 2025). The state of being infected such as from the introduction of a foreign agent such as serum, vaccine, antigenic substance or organism. "To test this possibility, we rescued the expression of either IRS-2 or IGF-IR by retroviral infection of FLAG-IRS-2 or IGF-IR-mRFP in siUSP9X cells, and assessed Erk1/2 phosphorylation." (PMID 30338032, 2018). "Similarly, IRS1 and IRS2 showed sustained downregulation throughout 12–72 h post-infection." (PMID 41294830, 2025). "Our data revealed that infection transiently elevated PI3K and AKT at early stages (12–24 h), followed by a marked reduction at later time points, along with decreased IRS1, IRS2, and GLUT1 expression." (PMID 41294830, 2025). "Here we found that genes IRS2, NRG1, HBEGF, and EREG regulating AKT signaling are downregulated in M-MDSC isolated from CoV2+ participants long after recovery from infection." (PMID 35812392, 2022). "Similarly in the LCMV-infected primate, IRS1 expression is decreased and expression of IRS2 is moderate, but SOCS2 is up-regulated (7.2-fold) at the pre-viremic stage of infection." (PMID 19216742, 2009). "Western blot analysis showed that infection with oe-lncARSR decreased YAP1, increased IRS2 expression and phosphorylation level of AKT, and did not affected AKT expression in oleate-treated cells, which was opposite in oleate-treated cells infected with sh-lncARSR." (PMID 32169080, 2020).
neurodegenerative disease (3 papers, 2021 to 2025). A disorder of the central nervous system characterized by gradual and progressive loss of neural tissue and neurologic function. "FOXO1 and IRS2 play important roles in the occurrence and treatment of tumors as well as in neurodegenerative diseases, but the association between their m6A modification and aging has rarely been reported." (PMID 36012545, 2022).
hematopoietic neoplasms (1 paper, 2016). "We have previously identified IRS2 phosphorylation to be upregulated during hematopoietic cell differentiation, although the functional role of IRS2 in hematopoietic neoplasms has not yet been addressed." (PMID 26755644, 2016).
kidney (1 paper, 2018). "Although more studies are needed, we propose that IRS2 is involved in pathological glycogen accumulation in the diabetic kidney and that the use of NaW in the context of altered IRS2 signaling induces abnormal renal glycogen accumulation that should be considered a new undesirable effect." (PMID 30003110, 2018).
IRS2 also shares sentences with these, for which no sentence is quoted: lung adenocarcinoma (4 papers); Cirrhosis (3); Ewing sarcoma (3); type 1 diabetes (3); adenocarcinoma (2); diabetic neuropathy (2); endothelial dysfunction (2); Hypoglycemia (2); nervous system diseases (2); Salmonella Infections (2); acute myocardial infarction (1); adenoma (1); anaphylaxis (1); angiitis (1); angina (1); Arthritis (1); Ataxia (1); B cell deficiency (1); bacterial infections (1); bladder urothelial carcinoma (1); blood disease (1); Cachexia (1); cardiac hypertrophy (1); cardiomyopathy (1); cervical squamous cell carcinoma (1); cholestasis (1); chronic hepatitis C (1); colon adenocarcinoma (1); colorectal adenoma (1); cyst (1).
A further 47 diseases each share a sentence with IRS2 in 1 paper.